NOX4 (NADPH oxidase 4)
Diseases named in the same sentence as NOX4 in open-access papers (continued):
Sharing a sentence is not in itself a finding about the gene and the disease.
Cerebral ischemia (27 papers, 2010 to 2025). Restriction of arterial blood supply to the brain associated with insufficient oxygenation to support the metabolic requirements of the tissue. "Similar to NOX2, NOX4-derived ROS have also been implicated in brain diseases, where ROS generation through NOX4 mediates neuronal damage in brain ischemia through NOX4-derived ROS from both endothelial cells and neurons." (PMID 37081190, 2023). "To date, NOX2 and NOX4 isoforms are the most implicated to contribute to ROS generation and pathology following cerebral ischemia." (PMID 29849881, 2018). "To date, NOX2 and NOX4 are the isoforms most implicated to contribute to ROS generation and pathology following cerebral ischemia, although there is also some evidence for NOX1 involvement as well." (PMID 28095923, 2017). "Our findings indicated that EA preconditioning could attenuate cerebral ischemia-reperfusion injury, and the underlying mechanism was related to reciprocal regulation; down-regulation of NOX4 and ROS production, while up-regulation of tight junction proteins." (PMID 26952102, 2016). "Among the known seven human members, the expression levels of NOX2 and NOX4 in microglia are high and seem to be up-regulated in response to brain injury and cerebral ischemia, respectively." (PMID 39652148, 2025). "NOX4 is also expressed and up-regulated in pericytes acutely after brain ischemia and its upregulation seems to enhance blood-brain barrier breakdown." (PMID 36897852, 2023). "More interestingly, NOX4 expression is elevated during hypoxia and brain ischemia model, after intracerebral hemorrhage and traumatic brain injury, all stress conditions associated with ROS excess and detrimental neuronal damage." (PMID 37081190, 2023). "Of these, NOX4 appears to be the most promising target for various diseases like neurodegenerative diseases or brain ischemia." (PMID 37760032, 2023). "Taken together, these studies suggest a critical role for Nox4 in maintenance of the BBB in the setting of cerebral ischemia." (PMID 36290688, 2022). "Pretreatment with betulinic acid was shown to downregulate levels of NOX4 and ROS after cerebral ischemia." (PMID 35154560, 2022). "In the case of local brain ischemia, NOX4 expression in brain cortex was evidently elevated, leading to increased ROS production." (PMID 31379960, 2019). "Knockout animal studies have further implicated NOX2 and NOX4 as the principal NOX isoforms involved in mediating oxidative stress and brain injury following cerebral ischemia." (PMID 28095923, 2017). "TLR4 activation is also known to upregulate NOX4 after rodent cerebral ischemia leading to the production of ROS." (PMID 26030867, 2015). "Genetic ablation or pharmacological inhibition of Nox4 has proven to have a remarkable neuroprotective role in a mouse model for cerebral ischemia." (PMID 22319452, 2012). "NOX4 is a major prooxidant enzyme in cerebral ischemia pathogenesis." (PMID 34539402, 2021). "In addition, following cerebral ischemia, mice genetically deficient in NOX4 (Nox4−/−) are largely protected from oxidative stress, neuronal death and BBB leakage." (PMID 33869275, 2021). "In addition, melatonin is able to decrease the expression of NADPH oxidase isoforms Nox2 and Nox4, reduces reactive oxygen species generation, and inhibits apoptotic cell death in a rat model of cerebral ischemia." (PMID 33102250, 2020). "Finally, in addition to the role for NOX2 in mediating cerebral ischemia brain damage, there is one report that showed NOX4 knockout mice have reduced oxidative stress and neurodegeneration following focal cerebral ischemia." (PMID 28095923, 2017). "Moreover, mice engineered to overexpress NOX4 in brain pericytes had significantly greater infarct volume after focal cerebral ischemia, along with enhanced reactive oxygen species production and blood–brain barrier breakdown in the peri-infarct region." (PMID 28095923, 2017).
Cerebral ischemia (continued). "Moreover, in MCAO (middle cerebral artery occlusion, a model that can simulate human cerebral ischemia) mouse, NADPH oxidase 4 (NOX4) expression was significantly upregulated in the pericytes surrounding the infarct tissue, and further destroyed the BBB by enhancing MMP‐9 activity." (PMID 40371544, 2025). "Notably, NOX4 is highly expressed in cerebral blood vessels and could contribute to ROS formation after acute cerebral ischemia." (PMID 35154560, 2022). "In addition, NOX4 was co-immunoprecipitated with TLR4 after cerebral ischemia in mice." (PMID 26030867, 2015). "Nox4 gene reconstitution experiments in Nox4−/− mice and studies of the effects of different, structurally unrelated NOX inhibitors—should they become available—would be desirable to further substantiate the causality between NOX4 deficiency and protection from cerebral ischemia." (PMID 20877715, 2010). "For instance, in some experimental models of retinal or brain ischemia, PPARα activation appeared to reduce ROS production by repressing genes like the NADPH oxidase-4 (Nox4)." (PMID 41301903, 2025). "Upon cerebral ischemia‐reperfusion, intracellular calcium increases, leading to the activation of NADPH oxidase 4(NOX4) and NOX5, two primary sources of oxidative stress." (PMID 34085418, 2021). "Of these NOX isoforms identified hitherto, NOX1, NOX2, and NOX4 are expressed in the brain and involved in BBB dysfunction after cerebral ischemia and reperfusion." (PMID 28690765, 2017). "For instance, it inhibited β-amyloid-induced neuroinflammation via the Nrf2/Keap1 pathway, alleviated high glucose-induced renal mesangial cell injury through the ROS/Nox4/ERK1/2 axis, and reduced cerebral ischemia-reperfusion injury by promoting neuronal survival and suppressing neuroinflammation." (PMID 41573542, 2025). "Drugs that selectively inhibit NOX4 (GKT136901) and NOX5(ML090) reduced BBB permeability, resulting in a significant reduction of infarct volume and direct neuroprotection when given immediately before or at the time of reoxygenation in a mouse model of cerebral ischemia‐reperfusion." (PMID 34085418, 2021). "Mice deficient in NOX4 (Nox4−/−) of either sex, but not those deficient for NOX1 or NOX2, were largely protected from oxidative stress, blood-brain-barrier leakage, and neuronal apoptosis, after both transient and permanent cerebral ischemia." (PMID 20877715, 2010).
myocardial infarction (27 papers, 2014 to 2025). Gross necrosis of the myocardium, as a result of interruption of the blood supply to the area, as in coronary thrombosis. "This study extends previous findings indicating that upregulation of P2X7R during myocardial infarction activates the Nox4/PERK/ATF4 pathway, which is known to regulate HIF-1α and VEGF." (PMID 41295364, 2025). "In mice subjected to LAD coronary artery ligation, administration of in vivo grade anti-NOX4 siRNA abrogated LV contractile dysfunction and attenuated myocardial infarct size and oxidative stress." (PMID 41009041, 2025). "Ultimately, NOX4 reduces the extent of myocardial infarction, underscoring the pro-survival effects of NOX4, which rely on spatially confined signal transduction within MAM." (PMID 38374992, 2024). "Our previous studies using both global Nox4KO and cardiomyocyte‐specific overexpressing mice demonstrated that cardiomyocyte Nox4 is protective against adverse remodelling in response to pressure overload and myocardial infarction." (PMID 33511759, 2021). "Our results were confirmed in a very recent study in a myocardial infarction model, where overexpression of Nox4 promoted M(IL4+IL13) polarization of cardiac macrophages and protects from postinfarction remodeling." (PMID 31178956, 2019). "•After myocardial infarction, Nox4-induced skewing of macrophage polarization toward an M2 phenotype is accompanied by a higher survival, decreased cardiac remodeling, and improved contractile function." (PMID 29445778, 2017). "•The reactive oxygen species–generating enzyme NADPH oxidase 4 (Nox4) is up-regulated in the heart after myocardial infarction." (PMID 29445778, 2017). "Cardiomyocyte-specific MRKO prevented the up-regulation of Nox2, Nox4 and ROS induced by myocardial infarction, suggesting that cardiomyocyte MR is important in regulating oxidative stress." (PMID 25354087, 2014). "The mechanistic studies confirmed that miR199a-5p could protect the heart from myocardial infarction injury by controlling the AGTR1/NOX4 and MARK4/VASH2/dTyr-tub pathways." (PMID 38956062, 2024). "To investigate the role of these proteins on diaphragm weakness in HFrEF, we generated inducible skeletal muscle specific knockouts of Nox2 or Nox4 using the Cre-Lox system and assessed diaphragm function in a mouse model of HFrEF induced by myocardial infarction." (PMID 36436728, 2023). "Similarly, NOX4 expression was raised in cardiomyocytes in response to pressure overload and after myocardial infarction in NOX4−/− mice and a cardiomyocyte-targeted NOX4 transgenic model." (PMID 36770715, 2023). "Thus, it was previously demonstrated that KDM3A plays a major role in the up-regulation of Nox2 and Nox4 expression in experimental myocardial infarction." (PMID 36552592, 2022). "Similarly, leonurine also prevents cardiac fibrosis and cardiac fibroblast activation following myocardial infarction by regulating the Nox4-ROS pathway and attenuate myocardial fibrosis after myocardial infarction by up-regulating miR-29a-3p." (PMID 36324522, 2022). "Following skeletal muscle-specific knockout of Nox2 or Nox4, we measured diaphragm contractile properties, fiber size, and mitochondrial function (respiration and ROS) in a mouse model of HFrEF resulting from ischemic cardiomyopathy induced by myocardial infarction." (PMID 36436728, 2023). "I/R injury as assessed in the current study simulates myocardial infarction, and our results suggest not only that a Nox4‐Akt‐InsP3R pathway may be important in mitigating injury but also that targeting the pathway (e.g., with an InsP3R blocker) could have therapeutic potential." (PMID 33001475, 2020). "The reactive oxygen species–generating enzyme NADPH oxidase 4 (Nox4) is up-regulated in the heart after myocardial infarction (MI)." (PMID 29445778, 2017).
myocardial infarction (continued). "Interestingly, in type 2 diabetes mellitus (Otsuka Long-Evans Tokushima Fatty-OLETF) rats, CANA treatment was shown to have a renoprotective action via reducing lipid peroxides (MDA + 4HNE) and NOX proteins (NOX2 and NOX4) in the kidneys when combined with fasting before myocardial infarction (MI)." (PMID 40227417, 2025). "The vital roles of Brd4 and its inhibitor JQ1 have been proven in the epigenetic regulation of p300 in various profibrotic genes, such as NOX4, snail family transcriptional repressor 1 (SNAI1), and CTGF in IPF and myocardial infarction (MI) induced cardiac fibrosis." (PMID 36864460, 2023). "Systemic NOX1, NOX2, and NOX1/NOX2 double KO mice showed a significant reduction in myocardial infarct size following I/R, while systemic NOX4 KO mice did not." (PMID 36770715, 2023). "NOX1, NOX2, NOX4, and NOX5 are expressed in the vascular wall and are related to different cardiovascular diseases (CVDs), such as atherosclerosis, hypertension, heart failure, or myocardial infarction (MI)." (PMID 32155782, 2020). "We also could firstly confirm that underlying ROS-related mechanisms entail inhibition of hypoxia-induced activations of NOX4, CTP1A, and MAPK pathways, which would hopefully add value to finding new therapeutic molecular targets for myocardial infarction." (PMID 30728885, 2019). "In the setting of acute myocardial infarction, pre‐treatment with guanabenz (which enhances eIF2α phosphorylation and increases ATF4 levels) largely corrected the deficit in Nox4 KO hearts but had no additional effect in WT hearts." (PMID 26742780, 2016).
thyroid cancer (27 papers, 2013 to 2026). "Here, we demonstrate that NOX4-derived reactive oxygen species (ROS) contribute to NIS repression in BRAFV600E-mutated thyroid cancer cells." (PMID 41694580, 2026). "In thyroid cancer, elevated NOX4 expression has been linked to increased oxidative stress, DNA damage, and genomic instability, which further contribute to tumor aggressiveness and progression." (PMID 40723913, 2025). "Although NOX4 seems to have a critical function in thyroid tumorigenesis, the pathways contributing to NOX4 association with thyroid cancer need to be figured out in depth." (PMID 35571253, 2022). "More recently, it was shown that NOX4 is also upregulated by BRAFV600E mutation in a TGF-β/Smad3-dependent pathway in thyroid cancer cells and that NOX4-derived ROS play a critical role in NIS repression induced by the oncogene." (PMID 30728883, 2019). "As shown in the immunoblot, NOX4 was positively regulated by endogenously p22phox expression, suggesting a role of p22phox in NOX4 associated signaling in thyroid cancer." (PMID 30367082, 2018). "Some researchers demonstrated that a BRAF mutation could increase NADPH oxidase 4 (NOX4) expression in thyroid cancer cells by the TGFβ/SMAD3 signaling pathway." (PMID 36157447, 2022). "However, 68.4% of PTC-BRAFwt also showed a high score of NOX4 protein, emphasizing that NOX4 expression could be upregulated in thyroid cancer independently of BRAF mutational status." (PMID 37504283, 2023). "Despite promising results, further research is needed to better understand the mechanisms regulating NOX4 expression and its role in the pathogenesis of thyroid cancer." (PMID 38089632, 2023). "The results of the study demonstrated that activation of the BRAFV600E pathway led to upregulation of NOX4 expression, which in turn resulted in the overproduction of ROS in thyroid cancer cells." (PMID 38089632, 2023). "The oncogenic effect of BRAFV600E in thyroid cells was shown to be mediated in part by TGF-β, and NOX4 is upregulated in thyroid cancer cells under the control of the BRAFV600E-TGF-β axis." (PMID 37504283, 2023). "Overall, we observed a high level of NOX4 protein in thyroid cancer tissues compared to normal adjacent tissues (92.9% of C-PTC, 52.9% of F-PTC, and 33.3% of ATC and 0% of NAT), which is consistent with previous reports with fewer tissues." (PMID 37504283, 2023). "It was also observed that NOX4 expression correlated with the presence of the transcription factor HIF-1α (hypoxia-inducible factor 1α) in thyroid cancer cells." (PMID 38089632, 2023). "concerned on the intracellular expression of the enzyme NOX4, a generator of ROS, in normal and cancer thyroid tissues aimed to investigate the role of NOX4 in the pathogenesis of thyroid cancer." (PMID 38089632, 2023). "NOX4 also participates in the regulation of other cancer types, including prostate cancer, gallbladder cancer, thyroid cancer, and ovarian cancer." (PMID 35646942, 2022). "NOX4 or p22phox downregulation decreases mitochondrial ROS in hypoxic thyroid cancer cells, impairs HIF1α stabilization, HIF1α-induced glycolysis increment, and cell proliferation." (PMID 35682803, 2022). "Among the NOXs, NOX4 was demonstrated to be upregulated in thyroid cancers such as PTC, so did its binding partner, p22phox." (PMID 35396551, 2022). "In thyroid cancer, knockdown of NOX4 and p22phox in hypoxia reduces ROS level, thus destabilizing HIF1α to restraining glycolysis and cell growth of TPC-1 cells." (PMID 35646942, 2022). "NOX4 knockdown decreased tumor growth in a thyroid cancer xenograft mouse model, demonstrating the functional implications of NOX4 in thyroid tumorigenesis." (PMID 35682803, 2022). "Due to our increased understanding of oxidative stress events in thyroid cancer, future therapeutics utilizing NOX4 inhibitors, either alone or in combination with other agents, must be studied." (PMID 35571253, 2022).
thyroid cancer (continued). "Most interestingly, enhanced NOX4 expression was reported in thyroid cancers and in thyroid cancer cell lines." (PMID 35269843, 2022). "In thyroid cancer cells, NOX4 has been shown to stabilize HIF1α in hypoxic conditions by increasing mitochondrial ROS, enabling cell proliferation." (PMID 35682803, 2022). "We first found that NOX4 expression directly corresponds to cancer progression in several tumor types: bladder urothelial carcinoma, thyroid carcinoma and esophageal carcinoma." (PMID 33557266, 2021). "In this study we demonstrate that NOX4 regulates thyroid cancer cell proliferation both in TPC-1 cells and xenografts." (PMID 30367082, 2018). "Using flow cytometry, the results showed that, the mitochondrial membrane potential was decreased when NOX4 was deleted in hypoxia, suggesting potent relevance between mitochondrial membrane potential and mROS under hypoxia in thyroid cancer." (PMID 30367082, 2018). "It was demonstrated that NOX4 and p22phox expression are upregulated in thyroid cancers, linking NOX4-dependent ROS generation to cancer development or progression." (PMID 30367082, 2018). "In the future, we further observe the effect of the NOX4 as a molecular target for thyroid cancer from the perspective of metabolism." (PMID 30367082, 2018). "Cell Counting kit-8(CCK8) assays displayed that TPC-1 proliferation with p22phox knockout in hypoxia was slowed down rather than normoxia, suggesting it is functionally consistent with NOX4 in regulating the proliferation of hypoxic thyroid cancer cells." (PMID 30367082, 2018). "Altogether, NOX4 reduces mitochondrial activity by decreasing oxygen consumption, mROS and mitochondrial membrane potential under hypoxia in thyroid cancer." (PMID 30367082, 2018). "Taken together, we provide a mechanism whereby NOX4 or p22phox functions as a tumor glycolytic regulator which is required for thyroid carcinoma proliferation." (PMID 30367082, 2018). "Similarly, NOX4 appears to play a crucial role in promoting thyroid cancer development, especially in PTC cases harboring the BRAFV600E mutation, which is associated with refractoriness to radioactive iodine treatment and cellular dedifferentiation." (PMID 40620232, 2025). "Such an observation is particularly important given the overexpression of NOX4 in thyroid cancer, especially in papillary thyroid carcinomas (PTC), where NOX4 has been linked to cancer pathogenesis through its role in generating H2O2 and promoting oxidative stress." (PMID 39513876, 2024). "Additionally, NOX4 has been found to be overexpressed in thyroid cancer, linking this H2O2-generating system to cancer pathogenesis." (PMID 39513876, 2024). "This suggests a potential role of NOX4 in the progression and aggressiveness of thyroid cancer." (PMID 38089632, 2023). "Taken together, the main conclusion of our study is that NOX4 expression could be a potential co-marker of thyroid cancer aggressiveness." (PMID 37504283, 2023). "Indeed, both NOX4 and p22phox are overexpressed in papillary thyroid cancers (PTCs), reinforcing the idea that thyroid cancer cells are under oxidative stress." (PMID 35682803, 2022). "Of note, NOX4 was found to be upregulated by BRAFV600E via a TGF-β-Smad3-dependent pathway in thyroid cancer cells and the level of NOX4 expression is increased in human and murine BRAFV600E-mutated thyroid tumors and inversely correlated with thyroid differentiation." (PMID 36497339, 2022). "NOX4 is required for mitochondrial ROS production in thyroid cancer cells under hypoxic conditions." (PMID 35682803, 2022). "NOX4 or p22phox downregulation increased NIS plasma membrane expression in thyroid cancer cells, showing that NIS subcellular location might be a redox-regulated process." (PMID 35682803, 2022). "We found NOX4 is upregulated as a function of the clinical histopathological grade in bladder urothelial carcinoma, thyroid carcinoma, and esophageal carcinoma, suggesting that NOX4 may be involved in cancer progression." (PMID 33557266, 2021).